MERTK (MER proto-oncogene, tyrosine kinase)
Diseases named in the same sentence as MERTK in open-access papers (continued):
Sharing a sentence is not in itself a finding about the gene and the disease.
cancer (continued). "Drugs targeting MERTK have been developed as agents for both reversing cancer progression and cancer immune evasion." (PMID 33381449, 2020). "We believe the profile of INCB081776 as a selective inhibitor of AXL and MERTK will provide an attractive potential treatment option for patients with cancer not only as a single agent, but also in rational combination with immunotherapeutic agents." (PMID 33425754, 2020). "In situ, MerTK expression was found within the immune infiltrate in multiple solid tumors, highlighting its potential role in cancer immunity." (PMID 33101282, 2020). "This suggests that targeting MerTK on leukocytes, including macrophages, has multiple arms of anti-cancer activity." (PMID 31088471, 2019). "The Akt pathways are funnels through which almost all cancers pass and as such are major therapeutic targets, the present results implicate MERTK as another potential target to decrease Akt activation." (PMID 30944303, 2019). "UNC569, UNC1062, UNC1666, UNC2025 and UNC2250 are MerTK small molecule inhibitors that have demonstrated anti-cancer activity in preclinical models." (PMID 31088471, 2019). "The TAM receptors (Tyro3, Axl and MerTK) are a well-studied family of receptors that, in addition to their function in many other cell types, including cancer cells, play roles in macrophage polarization and efferocytosis." (PMID 31088471, 2019). "There have been a few studies showing that MerTK inhibition, specifically on macrophages, is an effective anti-cancer therapy." (PMID 31088471, 2019). "Consistent with previous reports about MerTK in other malignant tumors, MerTK inhibition by either shRNA or treatment with UNC2250 attenuated invasion and migration in MCL cells, accompanied by decrease in phosphorylated FAK and total RhoA." (PMID 29554921, 2018). "The TAM receptors Tyro3, AXL, and MERTK are oncogenic drivers that promote survival, chemoresistance, and motility of cancer cells." (PMID 29382817, 2018). "Deregulation of the TAM (TYRO3, AXL, and MERTK) family of receptor tyrosine kinases (RTKs) has recently been demonstrated to predominately promote survival and chemoresistance of cancer cells." (PMID 28034848, 2017). "MerTK overexpression has been demonstrated in several cancer types such as melanoma, lung cancer, prostate cancer, glioblastoma, HCC, and head and neck cancer." (PMID 29285287, 2017). "We aimed to identify the prevalence of MerTK and p-MerTK surface expression among various cancer populations." (PMID 29285287, 2017). "The receptor tyrosine kinases (RTKs) TYRO3, AXL and MERTK (TAM) have well-described oncogenic functions in a number of cancers." (PMID 28727830, 2017). "The overexpression and hyperactivation of members of the TAM family of receptor tyrosine kinases – comprising TYRO3, AXL and MERTK is documented in many cancers." (PMID 28118606, 2017). "Collectively, these results suggested that RXDX-106, a MerTK inhibitor, has an anti-proliferative effect by reducing the p-ERK and p-AKT in MerTK activated cancer cells." (PMID 29285287, 2017). "Being the core machinery of host defense and survival, phagocytosis requires MerTK activation and cross-talks to autophagy, another metabolic and homeostatic regulating machinery adopted by cancer cells to improve their fitness." (PMID 29050198, 2017). "Due to the growing evidence of MERTK's involvement in different cancers several selective small molecule inhibitors have recently been developed and show promising pre-clinical results." (PMID 27081701, 2016). "MERTK overexpression is characteristic to several cancers and inhibition in those models has been found efficient." (PMID 25517981, 2014). "However, in the context of cancer, activated MERTK in macrophages polarizes them into a tumor-promoting phenotype and supports disease progression by creating an immunosuppressive microenvironment." (PMID 40725182, 2025).
cancer (continued). "This study focuses on the pursuit of several MERTK protein targets, which could have consequences for the development of novel therapeutics for various cancers." (PMID 41166341, 2025). "MerTK, the focus of this study, is typically expressed by immune cells (i.e., macrophages, dendritic cells, NK cells) but is overexpressed in many types of cancers, including TNBC." (PMID 40391157, 2025). "With its recognized advantages, quercetin may be a beneficial option in cancer combination therapy by targeting MerTK." (PMID 41195524, 2025). "MerTK is highly expressed in immune cells, vascular cells, and stem cells, affecting the pathological process of the three most common diseases in humans, such as brain disorders, cardiovascular diseases, and cancer." (PMID 38341954, 2024). "Thus, owing to their close linkage with the immune system, targeting MERTK in cancer offers promising therapeutic potential for improving patient outcomes across multiple cancer types." (PMID 39635932, 2024). "Moreover, many multi-kinase inhibitors have also be found to be effective in inhibiting MERTK and produce functional effects in cancer models." (PMID 39062902, 2024). "Chemoresistance mediated by MerTK has been detected in many types of cancer." (PMID 38545840, 2024). "So, the inhibition of both PS signaling and MerTK activation could be an additional strategy for cancer treatment." (PMID 38891056, 2024). "In particular, the exploration of MERTK inhibitors as part of combination therapies may yield new therapeutic options for patients with relapsed or refractory cancers." (PMID 39062902, 2024). "We previously reported that MerTK is expressed in various types of cancer, including TNBC." (PMID 38791148, 2024). "Therefore, the here reported increased MERTK expression on CD14+ cDC2s, with the highest expression detected in cancer patients, aligns with the known role of MERTK." (PMID 38242119, 2024). "The expression and activity of 5-LO in TAMs were reduced upon co-culture with dying cancer cells through Mer tyrosine kinase (MerTK)-dependent recognition of apoptotic cancer cells, which can be repressed by the proto-oncogene c-Myb at the transcriptional level." (PMID 37491279, 2023). "This raises the exciting possibility that ENPP1 inhibitors could act synergistically with MerTK blockade to clear cancer (see section I.1.4)." (PMID 37287967, 2023). "Indeed, based on the important functions of MerTK, many MerTK targeted therapies are in development to enhance outcomes for patients with a variety of types of cancers, and a few are in clinical trials." (PMID 35268561, 2022). "However, MERTK is over-expressed in many cancers, leading to aberrant efferocytosis and immune evasion." (PMID 36056187, 2022). "An important, newly discovered role of MERTK is as an innate immune checkpoint in cancer." (PMID 35969037, 2022). "Indeed, the MERTK inhibitor sitravatinib has been shown to circumvent resistance to immune checkpoint blockade in immunoresistant cancer types through its effects on the suppressive TIME." (PMID 35954340, 2022). "The upregulation of MERTK has been observed in many cancers." (PMID 33562150, 2021). "In addition to the oncogenic roles of MERTK in cancer cells, MERTK expressed in stromal cells contributes to the immunosuppressive microenvironment." (PMID 33562150, 2021). "Moreover, MerTK expression was more frequently observed in immune infiltrate than on cancer cells but rarely on both." (PMID 33101282, 2020). "Developing therapies which selectively target MerTK among TAM-R could be a promising approach to alleviate myeloid-mediated immunosuppression in cancer." (PMID 33101282, 2020). "Furthermore, it has been shown in many malignant tumors that MerTK is involved in the resistance of multiple anticancer therapies." (PMID 32370748, 2020).
cancer (continued). "In combination with TGFβ inhibition and radiotherapy our group blocked macrophage recognition of phosphatidyl serine on apoptotic cancer cells through genetic ablation of C-MER proto-oncogene tyrosine kinase (MerTK) which redirected immunosuppressive to inflammatory cytokine production." (PMID 30726287, 2019). "Consistent with this notion, unlike WT-SAV1, the cancer-associated SAV1-R233Q mutant was largely resistant to MERTK inhibitor -mediated suppression of Akt activation and displayed less sensitivity to UNC2025." (PMID 30944303, 2019). "The prevalence of MerTK protein overexpression was evaluated in 229 cancer tissue specimens." (PMID 29285287, 2017). "Aberrant expression of MERTK was observed previously in a variety of cancers." (PMID 29101300, 2017). "Second, overexpression of MERTK has been shown to induce efferocytosis in cancer cell lines." (PMID 25517981, 2014). "While the TLRs are primarily known for pro-inflammatory functions, our study identified the engagement of TLR2 receptors by cancer-secreted Hsp70 triggers anti-inflammatory MΦ M2 polarization through the induction of MerTK receptors on MΦs, followed by the association of Hsp70, TLR2, and MerTK." (PMID 39941817, 2025). "Similarly, in NSCLC, MERTK plays a contributing role in cancer progression." (PMID 39062902, 2024). "While radiotherapy-induced apoptosis of cancer cells has been reported to elicit effective systemic antitumor immune responses, MerTK expressed on macrophages may considerably suppress the activation of CD8+ T cells by promoting the efferocytosis of apoptotic cells by macrophages." (PMID 38443968, 2024). "Thus, macrophage MerTK activity is an attractive therapeutic target for cancer treatment." (PMID 38443968, 2024). "In these circumstances, MerTK gene therapy may enable immune cells to improve cell efferocytosis and enhance therapeutically exploit cancer immunotherapy to enhance immune cell clearance of dying cancer cells." (PMID 38341954, 2024). "Furthermore, given that a wide variety of cancers are known to express MerTK, including nearly 80-90% of AML patient samples, MerTK inhibitors could potentially have a dual cell intrinsic effect on AML cells and antitumor immune response through LAMs." (PMID 36960055, 2023). "Here, we show that TAM receptors MERTK and TYRO3 exert reciprocal effects in osteoblast biology: Osteoblast-targeted deletion of MERTK promotes increased bone mass in healthy mice and mice with cancer-induced bone loss, whereas knockout of TYRO3 in osteoblasts shows the opposite phenotype." (PMID 36509738, 2022). "Therefore, MERTK could represent a target to reduce cancer-induced osteoblast inhibition during osteolytic bone disease." (PMID 36509738, 2022). "Except for BAI1, CD31, and MerTK, the enhanced expression of Axl, Tyro3, Gas6, MFGE8, Stab2, Tim-4, CX3CL1, IDO1, Rac1, and PD-L1 was associated with decreased sensitivity to many drugs, which may partially explain the resistance to chemotherapy in cancers." (PMID 36059952, 2022). "In addition to our data, these results suggest that MerTK could hinder immunogenic cancer cell death response by inhibiting TLR pathways directly, and indirectly by inducing production of immunosuppressive cytokines such as IL-10." (PMID 33101282, 2020). "Consequently, MerTK inhibitors may promote cancer cell death, sensitize cells to chemotherapy, and act as new antiplatelet agents." (PMID 33114206, 2020). "Thus, a MerTK targeting strategy could present a dual effect on both reversing immunosuppression and slowing down cancer growth." (PMID 33101282, 2020). "However, targeting multiple TAM receptors may be advantageous as MerTK upregulation as a result of silencing or inhibiting Axl has been observed in several cancer models, suggesting the MerTK mediates resistance to treatments targeting Axl." (PMID 31088471, 2019).
cancer (continued). "Therefore, inhibition of MerTK may provide dual therapeutic effects against MerTK-expressing tumors by reducing cancer cell survival, invasion, and metastasis as well as stimulating antitumor immune responses." (PMID 29285287, 2017). "Notably, MerTK was stably maintained in both resistant cell lines in association with restored ERK and Akt phosphorylation, increased myosin phosphorylation and enhanced expression of fibronectin, the key regulators of cancer cell invasion." (PMID 29050198, 2017). "Proteins such as GDF15, MERTK, MRP2, SMPD-1, GPNMB, GRN, and FSTL1, while less widely recognized, have emerging roles in cancer progression, immune modulation, and metabolic regulation." (PMID 40805206, 2025). "Subsequently, we analysed the expression levels of these genes across 33 types of cancer and found that AXL, MERTK, TYRO3, CD24, HAVCR2 and CD47 exhibited higher expression levels, while TIMD4 and HAVCR1 showed relatively lower expression." (PMID 40576208, 2025). "Sitravatinib, a receptor kinase inhibitor targeting TYRO3, AXL, MERTK, and VEGFR2, is being studied in combination with nivolumab for various cancers." (PMID 39924521, 2025). "TYRO3, a member of the TYRO3, AXL, and MerTK (TAM) receptor tyrosine kinase (RTK) family, is upregulated in various cancers." (PMID 40299539, 2025). "This section reviews recent advancements in the use of key efferocytic proteins, such as MerTK, Axl, and GAS6, as clinical biomarkers for cardiovascular diseases, cancer, and inflammatory disorders." (PMID 41403915, 2025). "Since our data indicated that cancer cell EMD-CM induced MΦ M2 polarization, the involvement of MerTK in this process was tested." (PMID 39941817, 2025). "In recent years, MerTK has emerged as a possible target for treating solid tumors, ushering in the use of small molecule inhibitors against the TAM family of RTKs in many cancer types." (PMID 40391157, 2025). "There were strong connections via the GAS6-AXL/MERTK and THBS1-CD36/CD47/ITGA4/ITGB1/LRP1 axes between cancer cells (contributing ligands) and TAMs (contributing receptors)." (PMID 38169544, 2024). "Mer‐tyrosine kinase (MERTK), a member of the AXL, TYRO3, and MERTK (TAM) family, is one of the promising targets for cancer treatment." (PMID 39635932, 2024). "We were interested in SIRPα, MERTK and TREM2 because of their roles in the phagocytosis of cancer and apoptotic cells." (PMID 37483607, 2023). "High expression of merTK and CD47, for example, in CSCs and cancer cells would continue to promote their preservation while evading immune cell-mediated destruction." (PMID 38035101, 2023). "Using mouse models, Hyonchol Jang and Byung Il Lee at the National Cancer Center, Goyang, South Korea, and co-workers demonstrated that the drug BMS794833 is an effective inhibitor of MERTK-dependent efferocytosis." (PMID 36056187, 2022). "It is expressed in many human tissues and different types of cancers, and by binding to its three receptors (AXL, MERTK, TYRO3) plays a role in biological processes, i.e., proliferation, apoptosis, migration, and survival." (PMID 35626092, 2022). "In human carcinoma cells MDA-MB-231, HeLa, and MCF7, PD-L1 expression was shown to be upregulated by hyperactive MERTK and AXL signaling." (PMID 35572601, 2022). "The PtdSer, which is exposed on the apoptotic cancer cells, binds to PROS and Gas6 and transmits an “eat me” signal to the macrophages, which express abundant MERTK." (PMID 33562150, 2021). "Cancer cells that express high levels of TAM receptors, including MerTK, also express the ligands Gas6 and/or Pros1, as well as PtdSer on the outer membrane." (PMID 33801886, 2021). "Prostate CSCs expressed high levels of GAS6, suggesting that MERTK and/or AXL functions in cancer stem cells are related to their kinase activity." (PMID 34830794, 2021).
cancer (continued). "This review will focus on PtdSer as a cofactor required for stimulating TYRO3, AXL and MERTK – comprising the TAM family of receptor tyrosine kinases by their ligands Protein S (PROS1) and growth-arrest-specific 6 (GAS6) in inflammation and cancer." (PMID 31775787, 2019). "Further studies are needed to establish the exact mechanism of aberrant MerTK expression in MCL and other malignant tumors." (PMID 29554921, 2018). "Our data indicate that cancer cells secrete Hsp70, which acts on MΦ through TLR2 to upregulate MerTK and promote M2 polarization, a previously unknown functional connection between the TLR2 and MerTK pathways." (PMID 39941817, 2025). "A MERTK, a member of the TAM family, is one of the promising targets for cancer treatment among kinases as it plays a key role in cancer cell survival and proliferation along with the regulation of immune responses in cancer." (PMID 39635932, 2024). "To date, though no drugs have been approved for targeting the MERTK, however, there are a few analogs that have been explored in clinical trials for their therapeutic efficacy against cancer." (PMID 39635932, 2024). "Dual AXL/MERTK inhibitors such as ONO-7475, INCB081776, CT413, PF-07265807, and Q702, as well as pan-TAM inhibitors like RXDX-106, BMS-777607, and LDC1267, have also been found to be effective in cancer models." (PMID 39062902, 2024). "MerTK inhibition by ASO, in conjunction with these treatments, further influences the TME by modulating macrophage activity, which plays a critical role in both the innate and adaptive immune responses to cancer." (PMID 38443968, 2024). "The majority of TAM receptor-mediated efferocytosis studies with both cancer and non-cancer models focus on MerTK." (PMID 37644281, 2023). "In summary, MERTK and TYRO3 represent potent regulators of bone homeostasis with cell-type specific functions and MERTK blockade represents an osteoanabolic therapy with implications in cancer and beyond." (PMID 36509738, 2022). "To further investigate the contribution of the MERTK/Akt/SAV1 signaling in Akt activation triggered by growth signaling such as PI3K, we ectopically expressed a cancer patient-derived constitutively active H1047R-PIK3CA mutant in RCC cells depleted of endogenous SAV1." (PMID 30944303, 2019). "While numerous studies have described signalling pathways downstream of Axl and MerTK and the changes following stimulation with TAM ligands, relatively few studies have directly assessed signalling pathways downstream of Tyro3, particularly in cancers." (PMID 31766614, 2019). "As expected, MERTK was not phosphorylated, suggesting that this protein does not play a major role in cancer proliferation or drug resistance." (PMID 29386539, 2018). "MERTK is a transmembrane protein of the MER/AXL/TYRO3 receptor tyrosine kinase family, and is also a proto-oncogene that appears upregulated in cancers such as mammary tumours, cell lines from which have been shown to demonstrate an enhanced level of efferocytosis." (PMID 28813472, 2017). "In the present study, we demonstrate that AXL, but not TYRO3 or MERTK, is efficiently and sequentially cleaved by α- and γ-secretases in various types of cancer cell lines." (PMID 28034848, 2017). "Moreover, TAM (TYRO3, AXL, and MERTK) family also had negative influence on cancer immunotherapy by mediating efferocytosis, negative regulating of dendritic cell activity, and dysregulating production of chemokines." (PMID 36341335, 2022). "A recent report found that AXL, but not the other two members of the same family MERTK or TYRO3, is cleaved by α- and γ-secretases in cancer cell lines to generate an AXL intracellular isoform." (PMID 32992696, 2020). "In the present study, we systematically characterized the proteolytic process of TAM receptors and found that AXL, but not MERTK or TYRO3, is efficiently and sequentially processed by α- and γ-secretases in 7 types of cancer cells." (PMID 28034848, 2017).
cancer (continued). "We found that AXL-FL, but not MERTK or TYRO3, was very efficiently cleaved by α- and γ-secretases in various types of cancer cell lines." (PMID 28034848, 2017). "Previous studies proved that MerTK is not expressed in normal B and T lymphocytes, but in neoplastic B or T lymphocytes (such as B-ALL and T-ALL), so MerTK may be a therapeutic target in B or T cell-derived malignant tumors." (PMID 29554921, 2018).